GAD1 (glutamate decarboxylase 1)
Diseases named in the same sentence as GAD1 in open-access papers (continued):
Sharing a sentence is not in itself a finding about the gene and the disease.
schizophrenia (continued). "Genetic evidence has also supported the link between the GAD1 gene and schizophrenia." (PMID 33293518, 2020). "Gad1−/− rats also share some phenotypes with pharmacological models of schizophrenia." (PMID 33293518, 2020). "In conclusion, the loss-of-function mutation in the Gad1 gene causes not only cognitive impairments but also several behavioral alterations possibly relevant to positive and negative symptoms of schizophrenia." (PMID 33293518, 2020). "Reduced expression of the primary GABA-producing enzyme GAD67 (encoded by GAD1) and PV could then reflect adaptive reductions of inhibitory output, and are indeed seen in post-mortem cortical tissue from schizophrenia patients." (PMID 31824347, 2019). "Furthermore, the di- and trimethylation of H3K9 and H3K17, which are known to regulate GAD1 expression, were found to be elevated in cortical neurons in a postmortem study of patients with schizophrenia." (PMID 29991943, 2018). "This heterozygous KO mutant line showed MK-801 induced hyperlocomotion and sensorimotor deficits with a reduction in PV levels; conclusively demonstrating that haploinsufficiency of the Gad1 gene in a subset of GABA neurons is sufficient to recapitulate schizophrenia-related phenotypes." (PMID 29362511, 2018). "However, several conditional Gad1 deletion mouse lines have been tested for schizophrenia-related phenotypes with mixed results." (PMID 29362511, 2018). "Studies may also be carried out on antipsychotic-naïve schizophrenia patients to assess the treatment effects on GAD1 gene expression profile." (PMID 28122016, 2017). "For example, variations in the GAD1 gene can increase risk of schizophrenia, and schizophrenic patients who carry a single nucleotide polymorphism in this gene have increased GAD25/GAD67 ratios in the hippocampus, suggesting that an immature GABAergic system is retained." (PMID 24904277, 2014). "Interestingly, while antipsychotic treatment with haloperidol also impact on GABA receptor subunits and GAD1 expression in animal studies, these changes were in the opposite direction to our observations in schizophrenia." (PMID 22558445, 2012). "Recent studies of the hippocampus have suggested that a network of genes is associated with the regulation of the GAD67 (GAD1) expression and may play a role in γ-amino butyric acid (GABA) dysfunction in schizophrenia (SZ) and bipolar disorder (BD)." (PMID 22457755, 2012). "The promoter methylation of the GAD1 can inhibit the expression of GAD1 in schizophrenia." (PMID 21962230, 2011). "Among these 16 SZGenes, several (DRD2, GRIN1, GRM7 and GAD1) are related to three neurochemical hypotheses in the molecular mechanisms of schizophrenia, i.e., the dopamine, glutamatergic and GABAergic hypotheses." (PMID 20156358, 2010). "Notably, the schizophrenia subjects of the present study had lower GAD1 mRNA levels in comparison to the matched control." (PMID 17726539, 2007). "Given the importance of GAD67 for the pathophysiology of schizophrenia, it will be important to gain further insight into the molecular mechanisms that underly the reported GAD1 mRNA alterations in cerebral and cerebellar cortex of schizophrenia subjects." (PMID 17726539, 2007). "Unexpectedly, however, GAD1 DNA methylation in repressive chromatin (H3K27me3) of schizophrenia subjects was significantly different from control subjects: CpG methylation frequencies were on average 3.5% in the control cohort but only 0.4% in the disease cohort." (PMID 17726539, 2007). "Methylation patterns of CpG dinucleotides at the GAD1 proximal promoter and intron 2 were determined for each of the two chromatin fractions separately, using a case-control design for 14 schizophrenia subjects affected by a decrease in prefrontal GAD1 mRNA levels." (PMID 17726539, 2007).
schizophrenia (continued). "Notably, GABAergic dysfunctions, especially a decrease in GAD1 expression, are the most replicated findings in the schizophrenia postmortem brain, and might be regulated by histone modifications during brain development affecting GABAergic transmission." (PMID 36979236, 2023). "Some studies suggested that the overall reduction in GAD1 mRNA expression in schizophrenia might be predominantly due to a selective reduction in a certain subset of cortical interneurons, rather than due to a generalized reduction affecting all interneuron populations." (PMID 37131313, 2023). "GAD1, a gene encoding the GABA synthetic enzyme glutamate decarboxylase 67-kDa (also referred to as gamma aminobutyric acid 67, GAD67), is downregulated in patients with schizophrenia, which may contribute to the disinhibition associated with schizophrenia." (PMID 34746116, 2021). "Epigenetic regulation of the Gad1 promoter has already been shown to alter Gad1 expression levels with direct consequences for the balance between excitation and inhibition in brain regions involved in certain neuropsychiatric disorders such as autism, schizophrenia, and panic disorders." (PMID 33834423, 2021). "Alongside the reduced expression of PVALB and the GABA synthetic enzyme GAD1/GAD67 in PFC, hippocampus and thalamic reticular nucleus in schizophrenia, PNN structure is also compromised." (PMID 41317238, 2025). "Downregulation of SYP gene and decreased synaptophysin and GAD1 expression in HC and PFC due to the administration of MAM in rats and as well as in schizophrenia patients." (PMID 36692676, 2023). "For instance, RELN and GAD1 genes, as well as NR3B promotors, are epigenetically modified in schizophrenia, whereas the gene responsible for epigenetic genome modifications (DNMT1) is over-expressed in brains of schizophrenic patients." (PMID 37298431, 2023). "GAD1, the rate-limiting enzyme of GABA, is posited to contribute to GABA dysfunction in the brain of schizophrenia patients." (PMID 36980961, 2023). "Reduced full-length GAD1 transcript and GAD67 protein is a consistent finding in the postmortem brains of patients with several psychiatric disorders including schizophrenia, bipolar disorder and major depressive disorder." (PMID 33413507, 2021). "Similar to GAD1 mRNA, when analysed by diagnosis, GAD65/67 protein expression was significantly decreased by 34.14% in the midbrain of schizophrenia cases compared to controls (t(41.286) = 2.406, p = 0.021)." (PMID 34174930, 2021). "Decreased expression of the full-length GAD1 transcript and GAD67 protein is one of the most consistent findings in the brains of subjects with several psychiatric disorders, including schizophrenia, bipolar disorder and major depressive disorder." (PMID 33413507, 2021). "The reduction in gene expression of the GABA synthesis enzyme, GAD1, suggests that there is less production of GABA within neuron cell bodies in the midbrain in schizophrenia." (PMID 34174930, 2021). "Mice with GAD1 knocked down in Pv-FSI exhibited decreased GABAergic synaptic transmission and behavioral disruptions that align with phenotypes of schizophrenia, such as in sensorimotor gating deficits, fear, and novelty seeking." (PMID 34220586, 2021). "The network also includes some well-studied schizophrenia candidate genes (e.g., BDNF, DRD2, GRIN1 and GAD1)." (PMID 20156358, 2010). "Furthermore, it will be of interest to find out in future studies whether the observed DNA methylation deficits in H3K27me3-tagged GAD1 nucleosomes of schizophrenia subjects are specific for that gene, or part of a more widespread DNA methylation defect of the disorder." (PMID 17726539, 2007). "Some evidence indicates that DNMT inhibitors might regulate the expression of some genes related to schizophrenia (Reelin (RELN), GAD1)." (PMID 36979236, 2023). "Besides GAD1 expression, there is additional convincing evidence for the alterations of SST mRNA expression in schizophrenia." (PMID 37131313, 2023).
schizophrenia (continued). "GAD1 and GABA were first identified in neural systems and play critical roles in many neurological diseases, including Parkinson's disease, bipolar disorder, and schizophrenia." (PMID 36814556, 2023). "Schizophrenia, a neuropsychiatric disorder, also has abnormalities in the GABAergic system where the ratios of three genes related to GABA signaling are increased: GAD1 (GAD67 and GAD25), SLC12A2 (NKCC1), and SLC12A5 (KCC2) in the prefrontal cortex." (PMID 36771011, 2023). "We found reductions (21 – 44%) in mRNA encoding both presynaptic and postsynaptic proteins, vesicular GABA transporter (VGAT), GAD1, and parvalbumin (PV) mRNAs and four alpha subunits (α1, α2, α3, α5) of the GABAA receptor in people with schizophrenia compared to controls (p < 0.05)." (PMID 34174930, 2021). "In support of this, GAD1 mRNA is unchanged in the cortex of monkeys treated chronically with antipsychotics, and three schizophrenia cases with lower levels of cortical GAD1 mRNA, who were not on antipsychotics, also showed lower GABA-related transcripts." (PMID 34174930, 2021). "It is unknown whether there are molecular changes in GAD1, PV and SST transcripts in the midbrain in schizophrenia." (PMID 34174930, 2021). "GAD1 is expressed as both GAD67 and GAD25 mRNA transcripts with the former reported to have a lower expression level in schizophrenia compared to healthy controls and latter was reported to be predominantly expressed fetally, suggesting a role in developmental process." (PMID 28122016, 2017). "Thus far, epigenetic modulation of several genes, including GAD1 and RELN, has been found to be altered in schizophrenia." (PMID 23543703, 2013). "In contrast to our hypothesis, deficits in GAD1 mRNA were not exacerbated in the high inflammatory/schizophrenia subgroup." (PMID 34174930, 2021). "To test our hypotheses, we sought to determine in a human midbrain cohort (28/28 and 28/26 control/schizophrenia cases for mRNA and protein, respectively), whether GAD1 mRNA and GAD protein, as well as PV, SST and VGAT mRNA transcripts are lower in the midbrain in schizophrenia." (PMID 34174930, 2021). "Two of these mouse models (Pvalb/Gad1-silencing mice and PV-Cre; GAD67+/flox mice) showed altered prepulse inhibition and responsiveness to NMDA receptor antagonists and a partially schizophrenia-like phenotype but no apparent working memory impairment." (PMID 37168420, 2023). "Although this compensatory increase is not seen in schizophrenia, a higher level of GAD65 is not sufficient to prevent behavioral alterations in Gad1–/– rats." (PMID 37168420, 2023).
diabetes (105 papers, 2001 to 2026). "Intriguingly, most of the identified genes, which showed strong signals in normal islets but were potently suppressed by STZ, were previously linked with important β-cell functions or diabetes development, such as Slc2a2, Ucn3, Gad1, Cox6a2, Trpm6 and Vdr." (PMID 23828045, 2013). "STZ treatment also suppressed expression of a wide range of genes linked with key β-cell functions or diabetes development, such as G6pc2, Slc2a2 (Glut2), Slc30a8, Neurod1, Ucn3, Gad1, Isl1, Foxa2, Vdr, Pdx1, Fkbp1b and Abcc8, suggesting global β-cell defects in STZ-treated islets." (PMID 23828045, 2013). "Autoantibodies against GAD1 and GAD2 are elevated in type 1 diabetes mellitus and neurological disorders (see Further reading)." (PMID 29055034, 2017).
type 1 diabetes (93 papers, 2001 to 2026). "The autoimmune etiology of type 1 diabetes is also reflected by the presence of circulating autoantibodies, specific for β cell proteins including insulin (IAAs), 65-kDa isoform of GAD-1 and insulinoma-associated protein-2 (IA-2)." (PMID 20142874, 2009). "Glutamic acid decarboxylase 65 (GAD65; Gad2), one of the two mammalian enzymes that synthesize GABA from glutamate (the other being GAD67, Gad1), is expressed in human beta cells, and is a major autoantigen in type 1 diabetes (T1D)." (PMID 36246925, 2022). "The most important beta cell autoantigens in type 1 diabetes (Ins1/2, Slc30a8, Ica1, Gad1, Ptprn2) were expressed at higher levels in Zbed6-KO islets." (PMID 34296320, 2021). "GAD1 is a major autoantigen in type I diabetes and highly expressed in brain and pancreas." (PMID 32784936, 2020). "In type I diabetes mellitus, HLA-A, HLA-B, HLA-C, HLA-DPB1 and GAD1 exhibited significantly different expression levels." (PMID 26062681, 2015).
Anxiety (89 papers, 2011 to 2026). Intense feelings of nervousness, tension, or panic often arise in response to interpersonal stresses. "Our results showed that GAD1 “Nervousness or anxiety” was positively linked to many anxiety symptoms, such as CESD10 “Sleep disturbances” and CESD3 “Feeling blue/depressed”." (PMID 38347882, 2024). "Cross-symptom effects were also evident: CESD10 had the most pronounced longitudinal predictive effect on GAD1 (r = 0.105), indicating that sleep problems and physical tension not only co-occur with anxiety at the same time point but are also positively associated with subsequent anxiety levels." (PMID 41179821, 2025). "Associations of GAD1 candidate SNPs with dimensional anxiety traits." (PMID 22662185, 2012). "Anxiety symptoms (particularly GAD3, GAD2, and GAD1) became more central, while suicidal ideation shifted from a depression-specific cluster to one integrating anxiety symptoms." (PMID 40893605, 2025). "The strongest bridge edge was found between CESD10 (poor sleep quality) and GAD1 (r = 0.105), suggesting a mutually reinforcing relationship between sleep disturbance and anxiety experiences at the same time point." (PMID 41179821, 2025). "At T2, the symptoms with the highest strength centrality indices were GAD3 (Excessive Worry) (1.53), GAD2 (Uncontrollable Worry) (1.08), and GAD1 (Nervousness) (1.05), indicating a more prominent role for anxiety symptoms in the organization of the network." (PMID 40893605, 2025). "Interventions targeting bridge symptoms such as GAD1 (Nervousness or anxiety), CESD10 (Sleep disturbances), and CESD1 (Feeling bothered) have the potential to alleviate depressive and anxiety symptoms in this population." (PMID 38562253, 2024). "Concurrently, GAD1 (Nervousness or anxiety), CESD10 (Sleep disturbances), and CESD1 (Feeling bothered) stand as critical bridge symptoms between depression and anxiety disorders." (PMID 38562253, 2024). "Concurrently, we have also discerned that GAD1 (Nervousness or anxiety), CESD10 (Sleep disturbances), and CESD1 (Feeling bothered) stand as pivotal bridge symptoms between depression and anxiety disorders." (PMID 38562253, 2024). "GAD6 “Irritable”, GAD5 “Restlessness” and GAD1 “Nervousness or anxiety” were identified as the most critical bridge symptoms connecting anxiety and cognition." (PMID 39234623, 2024). "GAD1 (Glutamate Decarboxylase 1), the overall top biomarker for anxiety in this study, synthesizes gamma-aminobutyric acid (GABA) from glutamate." (PMID 36878964, 2023). "GAD1 in our studies modestly predicts clinically severe anxiety state in all patients in the independent testing cohort (AUC 58%, p = 0.04), with results being somewhat better in women (AUC 65%, p = 0.03)." (PMID 36878964, 2023). "Although fear conditioning is yet to be assessed, Gad1 ‘heterozygous’ KO mice show anxiety levels comparable to those of wild‐type (WT) mice." (PMID 33325157, 2021). "A previous study showed that knockdown of Gad1 from NPY+ cells led to reduced anxiety behaviors in adult mice." (PMID 30024942, 2018). "The link between BDNF-TrkB signaling and GAD1-GABA signaling plays an essential role in improvement of the anxiety state." (PMID 28872625, 2017). "BDNF-TrkB signaling is closely related to Gad1 expression in depression and anxiety, and regulates GABAergic mechanisms by inducing Gad1 expression." (PMID 28872625, 2017). "Among the strongest associations, robust links were observed between GAD1 (Nervousness) and GAD2 (Uncontrollable), as well as between GAD3 (Excessive Worry) and GAD4 (Trouble Relaxing), indicating strong interrelations among anxiety symptoms." (PMID 40893605, 2025). "Additionally, in terms of the BEI analysis, it was found that GAD1 (Nervousness or anxiety), CESD10 (Sleep disturbances), and CESD1 (Feeling bothered) were identified as the central bridge symptoms connecting depression and anxiety." (PMID 38562253, 2024).